RNU6-308P (RNA, U6 small nuclear 308, pseudogene)
Gene: Small nuclear RNA gene on chromosome 5 (95,521,369 to 95,521,475, forward strand). Ensembl gene ENSG00000212259.
Homologues: Orthologues: chimpanzee U6 (93% identical), macaque U6 (93% identical), rabbit U6 (84% identical), dog U6 (79% identical), guinea pig U6 (76% identical), guinea pig U6 (75% identical), pig U6 (75% identical). Paralogues in human: RNU6-1060P (84% identical), RNU6-1287P (83% identical), RNU6-371P (83% identical), RNU6-711P (83% identical), RNU6-1091P (82% identical), RNU6-1113P (82% identical), RNU6-1309P (82% identical), RNU6-422P (82% identical), RNU6-511P (82% identical), RNU6-742P (82% identical), RNU6-949P (82% identical), RNU6-1073P (81% identical), and 1287 more.